GRK3 (G protein-coupled receptor kinase 3)
Description:
Specifically phosphorylates the activated forms of G protein-coupled receptors. Such receptor phosphorylation initiates beta-arrestin-mediated receptor internalization, and signaling events leading to their desensitization. Phosphorylates the agonist-occupied form of the beta-adrenergic and closely related receptors (By similarity). Also phosphorylates ligand-bound C3a and C5a anaphylatoxin receptors (C3AR1 and C5AR1, respectively), leading to receptor desensitization. Positively regulates ciliary smoothened (SMO) signaling pathway by mediating phosphorylation of SMO, facilitating SMO trafficking into the cilium and the stimulation of SMO activity (By similarity).
Synonyms: ADRBK2; BARK2
Tractability: Small molecule: a high-quality ligand is known; it belongs to a druggable protein family. Antibody: its Gene Ontology location is reachable by antibodies, with high confidence; the Human Protein Atlas places it where antibodies can reach. PROTAC: UniProt records ubiquitination sites on it; ubiquitination databases record sites on it; a small molecule that binds it is known.
Target class: AGC protein kinase BARK subfamily; Kinase; Protein Kinase; AGC protein kinase GRK family; AGC protein kinase group; Enzyme
Gene: Protein-coding gene on chromosome 22 (25,564,432 to 25,729,294, forward strand). Ensembl gene ENSG00000100077.
Subcellular location: Postsynapse; Presynapse
Subcellular location (Human Protein Atlas): Nucleoplasm; Plasma membrane
Pathways (Reactome):
Signal Transduction: G alpha (s) signalling events
Vesicle-mediated transport: Cargo recognition for clathrin-mediated endocytosis
Gene Ontology:
Molecular function: G protein-coupled receptor kinase activity; protein binding; beta-adrenergic receptor kinase activity; G protein-coupled receptor binding; protein kinase activity; ATP binding; protein serine/threonine kinase activity
Biological process: desensitization of G protein-coupled receptor signaling pathway; receptor internalization; G protein-coupled receptor signaling pathway; signal transduction
Cellular component: cytosol; plasma membrane; postsynapse; presynapse; cytoplasm
Genetic constraint (gnomAD): Loss-of-function variants: 14 observed, 33.51 expected, observed/expected ratio (o/e) 0.42, 90% interval 0.28 to 0.65. The upper end of that interval is the gene's LOEUF score, 0.65, which puts it in group 2 of 6, group 1 being the genes least tolerant of losing a copy. Missense variants: 328 observed, 431.48 expected, observed/expected ratio (o/e) 0.76, 90% interval 0.69 to 0.83. Synonymous variants: 155 observed, 162.45 expected, observed/expected ratio (o/e) 0.95, 90% interval 0.84 to 1.09.
Homologues: Orthologues: chimpanzee GRK3 (100% identical), rabbit GRK3 (97% identical), pig GRK3 (96% identical), dog GRK3 (96% identical), macaque GRK3 (96% identical), tropical clawed frog grk3 (93% identical), mouse Grk3 (91% identical), guinea pig GRK3 (91% identical), rat Grk3 (91% identical), zebrafish grk3 (91% identical). Paralogues in human: GRK2 (84% identical), GRK6 (32% identical), GRK5 (31% identical), GRK4 (30% identical), GRK7 (27% identical), GRK1 (27% identical), RSKR (13% identical).
Diseases named in the same sentence as GRK3 in open-access papers:
GRK3 is named in the same sentence as 46 diseases in open-access papers, as found by Europe PMC text mining. Sharing a sentence is not in itself a finding about the gene and the disease. The quoted sentences say what the papers report.
breast carcinoma (11 papers, 2016 to 2024). "CDKL2 and GRK3 have been implicated in breast cancer progression and their overexpression correlates with poor prognosis." (PMID 31941153, 2020). "To test the effects of GRK3 on tumor growth and metastasis in vivo, we used GRK3-deficient mammary tumor cells derived from Balb/c (66cl4-luc) as a representative TNBC model system in an immunocompetent mouse." (PMID 27049755, 2016). "Since growth rates could impact metastatic potential in breast cancer, an in vitro assay was performed to assess intrinsic proliferation rates of GRK3-deficient and control 66cl4-luc cells." (PMID 27049755, 2016). "GRK3-deficient 66cl4-luc mammary tumors disseminate distant metastasis." (PMID 27049755, 2016). "The assays confirmed that CREB3L1, CAPG, and SPINT1 were significantly upregulated in breast cancer group, while GRK3 was significantly downregulated when compared to normal group, respectively." (PMID 39015775, 2024). "For example, we have shown previously that Grk3 overexpression in a line of metastatic breast cancer cells decreased CXCR4 internalization and increased cellular migration and metastasis in a mouse model of breast cancer." (PMID 37048054, 2023). "Decreased GRK3 expression correlates with basal-type breast cancer and liver metastasis in patients and alterations in GRK3 expression influence both migration and invasion of TNBC cells." (PMID 33096815, 2020). "Previous reports showed that the aberrant overexpression of GRK3 acts as a promoter mechanism in some kinds of tumors, including prostate cancer and breast cancer, especially in metastasis." (PMID 29445249, 2017). "In contrast, our results correlate GRK3 with breast cancer metastatic potential via regulation of tumor cell migration and invasion without significant effect on tumor growth or detachment-induced death." (PMID 27049755, 2016). "Analysis of public human breast cancer microarray data shows that only GRK3 and GRK5 isotypes are expressed at statistically significant lower levels in tumor cells compared to normal breast tissue." (PMID 27049755, 2016). "To predict the relevance of GRK3 in human breast cancer subtypes, we analyzed TCGA and publically available microarray data for GRK correlations with molecular subset distinction and metastasis." (PMID 27049755, 2016). "Our data emphasize the functional relationship of GRK3 as it pertains to CXCL12/CXCR4 migration in breast cancer and specific molecular subtypes." (PMID 27049755, 2016). "GRK3 was transiently overexpressed in the highly invasive MDA-MB-231 breast cancer cell line and confirmed by Western Blot." (PMID 27049755, 2016). "Besides, the opposite effects of GRK3 on the CXCR4-triggered metastatic progression of breast cancer is needed to be further validated in the GRK6-promoted TNBC metastasis." (PMID 39741338, 2024). "CREB3L1, CAPG, SPINT1, and GRK3 might be suitable for clinical application in early breast cancer treatment." (PMID 39015775, 2024). "More, stable GRK3 knockdown facilitates metastasis of xenografted breast cancer cells." (PMID 35281865, 2022). "Also, it is intriguing that GRK3 not only controlled survival and proliferation of breast cancer cells but also promoted primary breast cancer invasion and metastasis by dysregulated signaling through CXCL12/CXCR4." (PMID 29445249, 2017). "Recently, several lines of evidence suggest that GRK3 involved to the oncogenic process, which indicates that the aberrant expression of GRK3 acts as a promoter mechanism in some kinds of tumors, including prostate and breast cancer." (PMID 29445249, 2017). "Using established human breast cancer cell lines and an immunocompetent in vivo mouse model, we further demonstrate that alterations in GRK3 expression levels in tumor cells directly affect migration and invasion in vitro and the establishment of distant metastasis in vivo." (PMID 27049755, 2016).
breast carcinoma (continued). "The data show that relative GRK3 expression correlates with tumorgenicity, invasiveness, and metastatic potential in both human and mouse models and further, that manipulating GRK3 levels directly affects the chemotactic and metastatic potential of breast cancer cells." (PMID 27049755, 2016). "These authors acknowledge that GRK3 likely regulates other GPCRs that have relevance to cancer; in agreement with their speculation, the data presented herein describe an important functional role for GRK3 in regulating CXCR4 that impacts metastatic breast cancer progression." (PMID 27049755, 2016). "For example, downregulation of GRK2, GRK3, GRK5, and GRK6 promoted tumorigenesis and metastasis in Kaposi sarcoma, basal-like breast cancer, colon cancer, and medulloblastoma." (PMID 35769816, 2022). "It was shown that shRNA mediated downregulation of GRK3 in breast cancer cell lines led to an increased migration toward CXCL12, whereas overexpression of GRK3 diminished the chemotaxis." (PMID 34109182, 2021). "GRK3 is a critical determinant of cellular responses to proliferative and migration signals through CXCL12/CXCR4 in breast cancer." (PMID 29445249, 2017). "We now add G protein coupled receptor kinase 3 (GRK3) as an important regulator, specifically with respect to invasion and metastasis, in human breast cancer tissue, TNBC cell lines, and in an immunocompetent mouse model." (PMID 27049755, 2016). "The highly invasive breast cancer lines MDA-MB-231 and DU4475 had CXCR4:GRK3 mRNA expression ratios of 7:1 and 6:1, respectively." (PMID 27049755, 2016). "GRK3 regulates CXCR4-mediated migration and metastasis in breast cancer cell models." (PMID 34109182, 2021). "In our resected mouse mammary tumors, the CXCR4:GRK3 expression ratio was stable even after 6 weeks of tumor implantation and distant metastasis, suggesting that the CXCR4:GRK3 ratio is preserved and could be a useful prognostic indicator at extended times during the disease course." (PMID 27049755, 2016). "In breast cancer, the prognostic significance of GRK6 or its role in modulating cancer metastasis remains largely unknown even though GRK2 and GRK4, not GRK3, upregulation have been found to promote tumorigenesis, migration/invasion and metastasis in breast cancer cells." (PMID 39741338, 2024).
prostate carcinoma (9 papers, 2016 to 2022). A carcinoma that arises from epithelial cells of the prostate gland. "Their study demonstrated that CREB activation caused an increased expression of the GRK3 and neuroendocrine markers in prostate cancers previously managed with ADT." (PMID 33754118, 2021). "Finally, to directly examine a causal role of GRK3 in NED of prostate cancer cells, we overexpressed GRK3 wild type (WT) cDNA and kinase dead (KD) cDNA with a K220R mutation in LNCaP cells." (PMID 27191986, 2016). "Through shRNA and cDNA functional screening of human kinases, we previously identified that GRK3 (G protein-coupled receptor kinase 3) is an essential kinase for prostate cancer progression." (PMID 35996148, 2022). "We initially uncovered GRK3 as a key regulator of the progression of prostate cancer through unbiased shRNA and focused cDNA screening of human kinases." (PMID 32039001, 2019). "It is reported in the literature that GRK3 is highly expressed in prostate cancer cells and can promote angiogenesis and distant metastasis of prostate cancer." (PMID 31586103, 2019). "Genomic profiling and immunohistochemical staining of human prostate cancers showed that GRK3 is upregulated in advanced prostate cancers." (PMID 32039001, 2019). "In CREB-induced NED of prostate cancer cells, we have demonstrated, for the first time, that GRK3 can be a downstream mediator of CREB activation." (PMID 27191986, 2016). "To understand how GRK3 and NEPC progression contribute to poor prognosis in prostate cancer, we investigated the mechanisms of GRK3 overexpression in prostate cancer and its connections to ADT, CREB activation and NEPC development." (PMID 27191986, 2016). "We show that GRK3 indeed controls NED phenotypes of prostate cancer cells, and is induced by ADT as a direct target and critical mediator of CREB activation." (PMID 27191986, 2016). "To determine if the positive correlation between CREB and GRK3 exists beyond prostate cancer, we analyzed their expression patterns in ~1000 human cancer cell lines from the Cancer Cell Line Encyclopedia (CCLE)." (PMID 27191986, 2016). "Through unbiased shRNA and cDNA screening of hundreds of human kinases, we have shown that G-protein coupled receptor kinase 3 (GRK3) is a new critical activator of prostate cancer progression." (PMID 27191986, 2016). "Induction of GRK3 was also observed when we treated prostate cancer cells with beta-adrenergic receptor agonist isoproterenol (ISO), or adenylyl cyclase activator forskolin (FSK) with phosphodiesterase inhibitor IBMX (FSK+IBMX)." (PMID 27191986, 2016). "Moreover, GRK3 has oncogenic roles in different human cancers including prostate cancer, acute myeloid leukaemia, and pancreatic cancer, and its activity can be regulated by CREB in lung cancer." (PMID 34947968, 2021). "Hence, it appears that GRK3 represents a drug target for the treatment of patients with aggressive prostate cancers." (PMID 34947968, 2021). "GRK3 is essential for metastatic prostate cancer cells in culture and in mouse xenografts." (PMID 32039001, 2019). "The data presented in our previous and current studies suggest that targeting GRK3 may be a viable approach to inhibit prostate cancer progression and NEPC development." (PMID 27191986, 2016). "To further establish an essential role of the CREB-GRK3 axis in NED of prostate cancer cells, we next tested the hypothesis that upon GRK3 knockdown in NEPC cells, inhibition of CREB cannot further repress the expression of NE markers." (PMID 27191986, 2016). "GRK3-kinase dead form was also incapable to induce NE marker expression in prostate cancer cells." (PMID 27191986, 2016). "Moreover, overexpression of either the CREB wild type cDNA or constitutively active mutant CREB-Y134F cDNA increased the expression of NE markers and GRK3 in prostate cancer cells." (PMID 27191986, 2016).
prostate carcinoma (continued). "Furthermore, our results indicate a positive correlation of basal expression of CREB and GRK3 in human prostate cancer, normal tissues, and a broad range of human cell lines of many cancer types (CCLE)." (PMID 27191986, 2016). "However, it is unknown what biological processes are responsible for GRK3 overexpression in prostate cancers and how GRK3 contributes to prostate cancer progression." (PMID 27191986, 2016). "In neuroendocrine prostate cancer, the CREB/G-protein-coupled receptor kinase (GRK) 3 axis promotes neuroendocrine differentiation of the prostate cancer cells, whereas CREB activation is mediated by GRK3." (PMID 34947968, 2021). "Of note, we found a strong trend between GRK3 protein level and glomeruloid microvascular proliferation, a marker of VEGFA–driven angiogenesis, in prostate cancer patient samples." (PMID 32039001, 2019). "Mechanistically, GRK3 promotes prostate cancer progression in part through repressing two anti-angiogenic factors TSP1 and PAI2, thus inducing angiogenesis in prostate cancer cells." (PMID 32039001, 2019). "Although little is known of the effects of Grk3 on VSMC proliferation, it has been established that Grk3 plays an important role in the survival and proliferation of metastatic prostate cancer cells and in stimulation of tumor angiogenesis." (PMID 28659168, 2017). "Collectively, these results indicate that GRK3 is a critical activator of NE phenotypes, ADT resistance, and prostate cancer progression." (PMID 27191986, 2016). "To further strengthen these results from human prostate cancer cells and PDX models, we investigated GRK3 expression in a classic NEPC genetically engineered mouse (GEM) model, the TRAMP mouse." (PMID 27191986, 2016). "Taken together, these results indicate that GRK3 is a new critical activator of NE phenotypes and mediator of CREB activation in promoting NED of prostate cancer cells." (PMID 27191986, 2016). "We show GRK3 expression is higher in NEPC than in PAC cells and mouse models, and it positively correlates with the expression and activity of CREB in human prostate cancers." (PMID 27191986, 2016). "Taken together, our results demonstrate that GRK3 is a new activator for neuroendocrine phenotypes and ADT resistance in prostate cancer cells." (PMID 27191986, 2016). "We have reported that G protein-coupled receptor kinase 3 (GRK3, also called ADRBK2) promotes prostate cancer progression." (PMID 27191986, 2016). "GRK3 contribute to angiogenesis and metastasis through downregulation of several genes involved in angiogenesis and microenvironment modulation, such as TSP-1 and PAI-2 in prostate cancer." (PMID 29445249, 2017). "In this study, we have demonstrated that GRK3 is induced by androgen deprivation treatment (ADT) as a direct target of ADT-activated CREB, and that expression of GRK3 positively correlates with expression and activity of CREB in prostate cancer cells and tissues." (PMID 27191986, 2016). "To mimic castration-induced neuroendocrine differentiation in vivo, we compared the expression of GRK3 and NE markers between untreated PAC prostate cancer patient-deprived xenograft (PDX) LTL331 and NEPC PDX LTL331R that was derived from LTL331 after relapse from castration." (PMID 27191986, 2016). "Furthermore, we carried out analysis of the levels of GRK3 protein expression and CREB activation (by pS133-CREB) in a tissue microarray with 78 cases of human prostate cancer and normal samples." (PMID 27191986, 2016).